CCL15 (C-C motif chemokine ligand 15)
Diseases named in the same sentence as CCL15 in open-access papers (continued):
Sharing a sentence is not in itself a finding about the gene and the disease.
tumor (continued). "Among them, the chemokine family, including CC (e.g., CCL1, CCL3, CCL5, CCL7, and CCL15), CXC (e.g., CXCL1, CXCL3, CXCL5, and CXCL10), XC (e.g., XCL1 and XCL2), and CX3C (e.g., CX3CL1), plays a pivotal role in tumor development, metastasis, and chemotherapy resistance 30-33." (PMID 40740234, 2025). "Additionally, a study showed that Ccl15 expression in HCC patients correlates with a poor clinical outcome, increased tumor cell invasion and recruitment of immune-suppressive CD14+ monocytes." (PMID 38673795, 2024). "In short, CCL15 is able to promote the accumulation of TAMs in the TME and increase the drug resistance of tumor cells, so CCL15 may be used as a new target for anti-tumor therapy." (PMID 36173487, 2023). "Chemokines secreted by TAMs, including CCL3, CCL5, CCL15, CCL18, CXCL8 and CXCL12, promote tumor metastasis, angiogenesis, cancer cell survival, immunosuppression and resistance of cancer cells after chemotherapy via CCR1/5, CCR5, CCR1, CCR8, CXCR1/CXCR2, CXCR4, respectively." (PMID 36173487, 2023). "Moreover, it was recently found that CCL15 induced the recruitment of CCR1+ CD14+ monocytes to HCC invasive margin; in turn, monocytes suppressed the anti-tumor immune response and promoted tumor metastasis." (PMID 31991677, 2020). "EpCAM, IL8, CXCL10/IP10, CCL3/MIP-1α, CCL4/MIP-1β, CCL15/MIP-1δ, PDGFR-B protein were found to be expressed predominantly in tumours only, suggesting that they could be involved in the later stages of gastric tumorigenesis." (PMID 21092330, 2010). "The tumor-suppressive outcome is driven by combined molecular changes: downregulation of SPARCL1 and PSME3, coupled with upregulation of the NF-κB inhibitor NFKBIA and downregulation of CD44 and CCL15, collectively promotes apoptosis while suppressing proliferation, migration, and angiogenesis." (PMID 41465234, 2025). "However, we failed to observe correlation between CCL15 expression and tumor stage." (PMID 26875556, 2016). "In our study, we observed that CCL15 expression was significantly elevated in ESCC tumor tissues compared to adjacent nontumor tissues, and similarly, ESCC cell lines exhibited higher CCL15 levels than normal esophageal epithelial cells." (PMID 40740234, 2025).
cancer (36 papers, 2008 to 2025). A tumor composed of atypical neoplastic, often pleomorphic cells that invade other tissues. "Altogether, our results revealed another mechanism that PDAC cells utilize to self-promote cancer dissemination through oncogenic KRas mutations and its downstream targets CCL15 and ROS in order to enhance cell migration and invasion." (PMID 35565279, 2022). "Besides, six factors had inverse causal associations with cancer, including CCL15, CCL18, CCL19, CCL20, CCL21, and CCL28." (PMID 38075694, 2023). "The cancer-promoting effect of monocytes recruited by CCL15 might mask the causal association between CCL15 and cancer." (PMID 38075694, 2023). "We found that CCL15, a chemokine known to promote an immunosuppressive microenvironment and cancer metastasis, was significantly correlated with CRNKL1, SNRPB2, and PPWD1." (PMID 40282339, 2025). "Mechanistically, FAAH knockdown in cancer-associated fibroblasts (CAFs) attenuated co-cultured BLCA cell viability, potentially mediated by CCL15 secretion." (PMID 40630945, 2025). "TCGA database indicated that among several ligands, CXCL1, CXCL3, CXCL5, CXCL7 and CXCL8 (ligands for CXCR2) and CCL15 (ligand for CCR1) were particularly upregulated in CRC tissues compared with other cancers." (PMID 38750114, 2024). "In cancer, the cancer-promoting mechanism of CCL15 was mainly dependent on the monocytes it recruits, and MR Analysis was to analyze the causal association between CCL15 and cancer alone, without involving other factors." (PMID 38075694, 2023). "M2 macrophages expressing CCL15 related to the immunosuppressive microenvironment of the core regions of cancer tissues." (PMID 36459212, 2023). "Considering two mCCL9 homologs, human CCL23 and CCL15, these chemokines also display distinct functions that depend on, among others, the cancer type and the disease stage." (PMID 37185750, 2023). "A blockade of CCL15 in human metastatic PDAC Panc-1 cells, either through CCL15 knockdown or CCL15 neutralization, significantly impeded cancer cell motility as well as invasion." (PMID 35565279, 2022). "Based on the results of our microarray experiments, CCL15 was identified as a top-ranked target involved in the cancer progression of PDAC." (PMID 35565279, 2022). "Some chemokine receptors, such as cCCL27 (8 cancers), CCL28 (7 cancers), CCL16 (5 cancers), CCL17 (5 cancers), and CCL15 (four cancers), were negatively associated with pyroptosis in several cancers." (PMID 35246158, 2022). "Altogether, our work elucidates an additional molecular pathway of oncogenic Kras to promote PDAC metastasis through the upregulation of cell migration and invasion by the Kras downstream CCL15, a lesser-known cytokine within the cancer research field." (PMID 35565279, 2022). "To assess if CCL15 plays a role in cancer metastasis, we first examined the levels of CCL15 mRNA and protein expression in cultured human PDAC cell lines that have different metastatic abilities when implanted into mice." (PMID 35565279, 2022). "If the cancer cell stops in the bone, CCL15, produced by the cancer cell, acts chemotactically on osteoclast precursors and osteoclasts, probably via CCR1 and CCR3." (PMID 33182504, 2020). "Increased CCL15 and CCL20 expression has been reported in a number of cancers and is associated with a poor prognosis." (PMID 32560387, 2020). "However, there was an inverse association between CCL15 and CCL18 and cancers in our analysis." (PMID 38075694, 2023). "There are 28 types of chemokines (CCL1-CCL28) belonging to the CC chemokine subfamily, among which CCL2, CCL3, CCL5, CCL15, CCL18 and CCL26 exert some regulatory effects on pathological processes such as TAMs infiltration and polarization in cancer." (PMID 36173487, 2023). "Three of these proteins—CCL15, CHGA, and KLK10— are known to be prognostic markers for various types of cancer, and upregulation of these proteins is correlated with poorer prognosis." (PMID 36613555, 2022).
cancer (continued). "For other chemokines, CXCL11 was positively related to approximately all other chemokines except CCL14, CCL15, CCL16, CCL27, CCL28, CXCL6, and CXCL17 in almost all types of cancers." (PMID 35935945, 2022). "In our current study, the expression levels of CCL15 and CXCL7 (PPBP) were decreased in cancer tissues compared with the adjacent normal tissues." (PMID 36118890, 2022). "Other genes overexpressed in Cluster 1 were chemokine and cytokine related genes (CCL15, CCL18, TNF, IL11RA, XCR1), the immune checkpoint protein PD-1 (PDCD1), and cancer-related genes (SSX1 and MAGEA4)." (PMID 33298930, 2020). "Similarly, CM of the cancer cell line HT29, which constitutively expresses CCL15, induces MC migration that is significantly diminished in the presence of a CCL15-blocking antibody." (PMID 35159157, 2022). "CCL15 was also increased as the pseudo-time progressed and was dominant in the end stages of the pseudo-time axis; Conversely, other key molecules such as IGHG1, IGHG3, IGHG4, IGKC, IGLC2 decreased gradually among all the carcinoma sectors in HCC1 and HCC4." (PMID 35673582, 2022). "Notably, the recruitment mechanisms (CCL15 vs CXCL5/CXCL1/8) and effector molecules (VEGFC-dominant vs MMP9/VEGFA-cooperative) display cancer-type specificity, suggesting evolutionary selection for distinct molecular implementations of a conserved TANs-lymphatic metastasis principle." (PMID 40739091, 2025). "CCL27 and CCL15 showed negative correlations with necroptosis levels in certain cancers." (PMID 36170029, 2022). "We also presented the spatial features and relatively quantified the levels of CCL15 among 4 samples, which revealed that CCL15 was obviously upregulated in the carcinoma sector of HCC1 and HCC4, however, no distinct and similar difference in HCC2 and HCC3 was observed." (PMID 35673582, 2022). "CCL15, CCL14, CCL16, CCL23, and CCL27 showed negative relations in more than 10 cancers." (PMID 38655053, 2024).
infection (7 papers, 2014 to 2025). The state of being infected such as from the introduction of a foreign agent such as serum, vaccine, antigenic substance or organism. "Following infection of ESCC cells, cell proliferation assays showed that CCL15 knockdown significantly inhibited cell proliferation." (PMID 40740234, 2025). "The infection of MDMs with Mtb opsonized with hSAA-1, compared to the infection with nonopsonized bacilli, led to at least a 2-fold increase in the concentrations of CSF2, CSF3, IL-1α, IL-1β, IL-6, IL-12, CCL15, and TNF-α with the most potent 10-fold increase observed for CCL5." (PMID 37781389, 2023).
inflammation (2 papers, 2018 to 2022). Aberrant reaction of the microcirculation characterized by movement of fluid and leukocytes from the blood into extravascular tissues. "Increased levels of CCL15 in the lung have been associated with airway inflammation." (PMID 30595762, 2018). "Whether the human homologue CCL15 could exert comparable effects or would be a useful biomarker of kidney inflammation and fibrosis, remains to be investigated in future studies." (PMID 35203629, 2022).
kidney disease (2 papers, 2015 to 2021). "Eighteen differentially expressed proteins were found to overlap between the CKD and post-transplant CKD groups including biomarkers of kidney disease (cystatin C, β2-microglobulin, and REN) and biomarkers of inflammation (CFD, IGFBP-2, PRSS 2, Chemokine Ligand 15 (CCL-15), and TNFRSF-1B)." (PMID 33888746, 2021).
CCL15 also shares sentences with these, for which no sentence is quoted: dementia (2 papers); endometriosis (2); pseudoexfoliation glaucoma (2); sarcoidosis (2); Alzheimer disease (1); autism (1); autoimmune disorders (1); benign tumors (1); bone metastasis (1); cataract (1); choroidal hemangioma (1); Cirrhosis (1); colorectal tumor (1); coronary atherosclerosis (1); depression (1); developmental delays (1); diabetic eye disease (1); focal segmental glomerulosclerosis (1); glaucoma (1); glomerular diseases (1); Hypertension (1); keloid (1); leptospirosis (1); leukemia (1); Löfgren’s syndrome (1); lung adenocarcinoma (1); lymphoma (1); mucinous ovarian cancer (1); non-small cell lung carcinoma (1); osteoporosis (1).
A further 18 diseases each share a sentence with CCL15 in 1 paper.